STK11 (serine/threonine kinase 11)
Diseases named in the same sentence as STK11 in open-access papers (continued):
Sharing a sentence is not in itself a finding about the gene and the disease.
osteoporosis (1 paper, 2023). A condition of reduced bone mass, with decreased cortical thickness and a decrease in the number and size of the trabeculae of cancellous bone (but normal chemical composition), resulting in increased fracture incidence. "In addition, a relationship between STRADA and STK11 overexpression in glucocorticoid-induced osteoporosis was described." (PMID 36833439, 2023).
penile cancer (1 paper, 2013). A primary or metastatic malignant neoplasm that affects the penis. "The present results suggest that single nucleotide mutations and/or deletions of STK11 gene are rare events in penile cancer." (PMID 23305393, 2013). "The results obtained in our study showed that STK11 exon 1 and 2 are deleted in 11.5% of penile cancers." (PMID 23305393, 2013). "The results obtained so far allow to conclude that single nucleotide mutations and/or deletion of STK11 gene are rare events in penile carcinoma suggesting that STK11 genetic alterations do not have a relevant role in the pathogenesis of penile cancer." (PMID 23305393, 2013). "The aim of the present study was to analyze genetic alterations and single nucleotide mutations in exons 1 to 9 of STK11 gene in HPV-positive and HPV-negative penile cancers to possibly establish a relationship between HPV infection and genetic alterations involved in cancer progression." (PMID 23305393, 2013). "The nucleotide sequence analysis of exons 1 to 9 of STK11 in 5 penile carcinoma cases showed no somatic mutations in none of the 9 coding regions." (PMID 23305393, 2013). "No studies have been performed on STK11 mutational status in penile carcinoma." (PMID 23305393, 2013).
penile squamous cell carcinoma (1 paper, 2013). "In this study we investigated STK11 somatic mutations in both HPV-positive and HPV-negative penile squamous cell carcinoma cases, in order to verify a potential role of this tumor suppressor gene in penile tumorigenesis." (PMID 23305393, 2013). "Genomic DNAs extracted from 26 cases of penile squamous cell carcinoma were analyzed for genetic alterations in the exons 1 to 9 of STK11 gene by quantitative real-time PCR." (PMID 23305393, 2013).
Pleural effusion (1 paper, 2025). The presence of an excessive amount of fluid in the pleural cavity. "After progression, an STK11 intronic loss-of-function mutation (c.734 + 1G.T) was detected as a resistance mechanism through liquid biopsy using pleural effusion and plasma." (PMID 41246301, 2025).
Rothmund-Thomson syndrome (1 paper, 2022). "Mutation of RecQ protein-like 4 (RECQL4) causes Rothmund-Thomson syndrome, and the STK11/LKB1 gene mutation results in dysfunction of UV-induced DNA damage responses and hyperpigmentation." (PMID 35087618, 2022).
Streptococcus infection (1 paper, 2020). "It has previously been shown that mice with systemic autophagy ablation have a life span of 2–3 months and the mortality is due to initial Streptococcus infection and eventual neurodegeneration, whereas, adult mice with whole-body Stk11 deletion survive for up to 6 weeks." (PMID 33236987, 2020).
syndromic (1 paper, 2025). "In this study, we focused on syndromic disorders caused by seven tumor suppressor genes: FH, NF1, PTCH1, RB1, STK11, and TSC1/2." (PMID 40702147, 2025).
thoracic tumors (1 paper, 2023).
vascular tumors (1 paper, 2019). "This uncouples mTORC1 activation from growth factor signaling such as mutations of liver kinase B1/serine/threonine kinase 11 (LKB1/STK11) in nutrient-deprived vascular tumors but allows activation of mTORC1." (PMID 31075885, 2019).
venous thromboembolism (1 paper, 2022). Occlusion of the lumen of a vein by a thrombus that has migrated from a distal site via the blood stream. "Somatic tumor mutations in STK11, KRAS, CTNNB1, KEAP1, CDKN2B and MET, which were reported to be associated with cancer-induced venous thromboembolism in an independent study, were infrequent in OSCC." (PMID 35053621, 2022).
vulvar carcinoma (1 paper, 2025). "Moreover, the two tumor components of the thyroid harbored identical mutations in KEAP1, RB1, and STK11, none of which were detected in the vulvar carcinoma." (PMID 40600748, 2025).
tumor (1,241 papers, 1999 to 2026). "In the context of STK11 loss, tumor cells exploit multiple mechanisms to evade KRAS G12Ci therapeutic pressure." (PMID 41541668, 2026). "Tumor loss-of-function mutations in STK11/LKB1, a regulator of AMP-activated protein kinase, induce cancer cachexia (CC) in preclinical models and are linked to weight loss in non-small cell lung cancer (NSCLC) patients." (PMID 41617691, 2026). "In this review we present an overview of STK11 function and its role in tumor biology, highlight the prognostic and predictive potential of STK11 mutations in the context of NSCLC treatment and summarize the emerging treatment strategies." (PMID 42187558, 2026). "STK11 mutations are mostly enriched in tumours, expressing high TMB levels with a “cold” tumour immune microenvironment, characterised by reduced density of effector T lymphocytes and increased density of neutrophils." (PMID 40650126, 2025). "STK11 is a major tumor suppressor gene, and pathogenic STK11 variants have been detected in a variety of disseminated cancers." (PMID 40860288, 2025). "STK11 is a tumor suppressor, and its loss-of-function mutations are implicated in Peutz–Jeghers syndrome (PJS) and various human cancers." (PMID 41051525, 2025). "PJS is caused by germline pathogenic variants in the tumour suppressor gene STK11/LKB1, with subsequent somatic inactivation of the wild-type allele then resulting in loss-of-function of the kinase activity of LKB1." (PMID 40426219, 2025). "For instance, in lung adenocarcinoma, STK11 variants alter the tumor immune microenvironment by affecting CD1E expression, which regulates the differentiation of macrophages." (PMID 40860288, 2025). "STK11 (also known as LKB1) encodes a tumor suppressor involved in cellular energy homeostasis, polarity regulation, and cell adhesion." (PMID 41203783, 2025). "In non-small cell lung cancer (NSCLC), the Stk11/Lkb1 gene is subject to deletions and mutations, which contribute to the resistance of tumor patients to PD-1/PD-L1 inhibitors." (PMID 40936907, 2025). "For example, increased glycolysis and lactate production, particularly in tumours harbouring STK11 mutations, suppress antitumour immunity, thereby exacerbating resistance to ICIs." (PMID 40277912, 2025). "Several STK11 kinase motifs have also been identified as mutational hotspots in pan-cancer tumour sequencing surveys." (PMID 40791513, 2025). "Genetic loss of STK11 remodels the tumor cytokine milieu, inducing upregulated expression of proinflammatory mediators—including CXCL7, G-CSF, IL-1β, and IL-6—which promotes neutrophil recruitment and suppresses T-effector cell function." (PMID 41254689, 2025). "Specifically, stk11 encodes a serine/threonine kinase involved in cellular polarity and tumor suppression, while atp1a2 has been shown to inhibit tumor growth in vivo." (PMID 40941396, 2025). "The identification of a somatic STK11 mutation via tumor WES highlights its potential role in tumorigenesis but does not imply germline predisposition or hereditary risk." (PMID 39895895, 2025). "STK11 (also known as LKB1) is a tumor suppressor gene that encodes a protein critical for regulating cellular metabolism, polarity, and proliferation." (PMID 40289841, 2025). "A cohort study has demonstrated that mutations in tumor suppressors, such as STK11, are correlated with a poor prognosis for malignant tumors." (PMID 39955067, 2025). "Germline mutations in STK11 (OMIM #602216), which encodes serine/threonine kinase 11, a tumor suppressor that has roles in apoptosis, cell cycle arrest, cell proliferation, cell polarity, and energy metabolism, have been identified as the sole cause of PJS." (PMID 40830517, 2025). "For instance, the inactivation of the tumor suppressor gene serine/threonine kinase 11 (STK11) in KRAS-mutated LUAD shifts the TME toward tumor infiltration by immunosuppressive neutrophils and the reduction of PD-L1 expression in cancer cells and less TILs." (PMID 39995659, 2025).
tumor (continued). "This leads to a starker separation between EGFR-mutant and KRAS-mutant tumours, while also highlighting the association of other events such as STK11 mutation in the determination of which evolutionary trajectory a tumour will follow." (PMID 41509216, 2025). "A cold tumour microenvironment is the most common explanation for the association between STK11 mutation and low PD-L1 expression, as well as a worse response to immunotherapy." (PMID 40650126, 2025). "Our map holds potential clinical value both for diagnosing and informing therapy for those with PJS, and also for those with NSCLC or other tumours bearing STK11 variants." (PMID 40791513, 2025). "We subsequently investigated the influence of KEAP1/STK11 mutations on established biomarkers of immunotherapeutic response, such as PD-L1 expression and tumor mutation burden (TMB)." (PMID 41378285, 2025). "STK11/LKB1 loss also remodels the tumor microenvironment through PI3K/AKT–FOXO axis-mediated apoptosis suppression and aberrant activation of Wnt/β-catenin and Notch pathways, driving epithelial–mesenchymal transition (EMT) and cancer stemness." (PMID 41573642, 2025). "The proliferation of tumor cells is closely linked to their metabolic activity, with STK11 playing a key molecule in this mechanism." (PMID 41031049, 2025). "This case reveals a potential novel role of STK11 in renal embryogenesis, expanding its phenotypic spectrum and challenging the conventional paradigm that STK11 mutations solely confer tumor predisposition." (PMID 40676516, 2025). "From the initiation of anti-PD-1 treatment, factors such as tumour mutational burden, specific mutations (e.g., STK11, KEAP), clonal architecture, aneuploidy, immune-escape mechanisms, and interferon-γ signalling pathways have all been linked to resistance." (PMID 41010951, 2025). "In contrast, co-occurring STK11/KEAP1 mutations, probably due to the STK11 impact on “cold” tumour microenvironment, lead to lower levels of PD-L1 expression and decreased response to immunotherapy." (PMID 40650126, 2025). "STK11 can encode tumor suppressor liver kinase b1(Lkb1), an important enzyme that promotes dendritic cell maturation and functions as a tumor antigen presenter." (PMID 40696413, 2025). "Certain mutations in STK11, particularly those affecting its regulatory domains, significantly impact its tumor-suppressive functions (Kinzler and Vogelstein, 1996, Sanchez-Cespedes, 2007)." (PMID 39895895, 2025). "STK11 mutant tumours show strong immune downregulation associated with a neutrophil degranulation signature." (PMID 40849356, 2025). "STK11 mutated tumours facilitate immune evasion by reducing antigen presentation through decreasing the expression of immunoproteasome components that generate immunogenic peptides for presentation by MHC-1." (PMID 40650126, 2025). "Loss of STK11 function due to mutation is common in many tumour types, including NSCLC, with an incidence of up to 15% of patients." (PMID 40650126, 2025). "Somatic mutation of STK11 (serine/threonine kinase 11), a tumor suppressor, occurs in the MSK-IMPACT platform in 1.9% of 3116 breast cases." (PMID 41051525, 2025). "STK11 has been found to primarily act as a tumor suppressor in cancer, and loss-of-function mutation in STK11 contributes to cancer progression." (PMID 38205151, 2024). "The key tumor alteration driving primary resistance to immunotherapy seems to be the STK11 inactivating variant, which is present in the primary adenocarcinoma." (PMID 39045411, 2024). "Previous research revealed that STK11 alteration was associated with tumor differentiation, invasion, early lymph node metastasis and TNM stage." (PMID 38632512, 2024).
tumor (continued). "The STK11 gene, formerly known as LKB1 (Liver Kinase B1), encodes the enzyme Serine/Threonine Kinase 11 (NP_000446.1) that is considered to be a “master kinase” and functions as a tumor suppressor." (PMID 39011112, 2024). "The STK11 gene codes for liver kinase B1, a highly conserved serine/threonine kinase, is implicated as a tumour suppressor in epithelial cancer invasion and metastasis." (PMID 39530091, 2024). "The STK11 gene is located on chromosome 19p13.3 and encodes a serine/threonine kinase that plays a crucial role in cell growth regulation and tumor suppression." (PMID 38800180, 2024). "At the molecular level, loss of the LKB1 tumour suppressor (also known as STK11) is observed in several malignancies including, notably, over 30% of human LUADs." (PMID 39048991, 2024). "STK11 was first shown to be mutated in Peutz–Jeghers syndrome and was later discovered to be an essential tumor suppressor." (PMID 38461159, 2024). "It is attributed to mutations in the serine/threonine kinase 11-LKB1 (STK11/LKB1) tumor suppressor gene located on chromosome 19p13.3." (PMID 39626430, 2024). "The STK11 gene, located on chromosome 19p13.3, encodes a serine/threonine kinase involved in cell growth regulation and tumor suppression." (PMID 38800180, 2024). "Our data identifies the transcriptional effector YAP1 as impacting tumor-intrinsic gene expression in STK11-deficient, KRAS-driven human LUAD cell lines." (PMID 37968341, 2024). "This patient’s plasma circulating tumor DNA (ctDNA) revealed the presence of a novel STK11 frameshift mutation." (PMID 39802954, 2024). "In selected cases enrichment of cancer gene mutations, such as copy number gain of MYC and KRAS, and pathogenic variants of IDH1 and STK11, was observed in residual tumor cells following study therapy." (PMID 38689060, 2024). "Using multiple KRAS-driven human LUAD cell lines, our work demonstrates that STK11 loss results in altered tumor-intrinsic cytokine expression, including but not limited to IL-6, CXCL8 and CXCL2." (PMID 37968341, 2024). "According to the available literature, STK11 mutation is associated with the immunosuppressive tumor microenvironment, which acts as a barrier against some anti PD-1/PD-L1 antibodies in NSCLC." (PMID 38736875, 2024). "Despite canonical activation by the upstream kinase and well-established tumour suppressor, LKB1 (aka STK11), NUAKs are implicated in a number of roles more commonly associated with tumour development and cancer progression." (PMID 38939918, 2024). "Another tumor suppressor frequently mutated in LUAD is STK11, also known as LKB1, which encodes a kinase protein that regulates an important energy sensor in cancer cells, i.e., AMP-activated protein kinase (AMPK)." (PMID 39538085, 2024). "The STK11 gene (19p13.3) encodes the STK11–Serine/Threonine Kinase 11 (433 amino acids; 48,636 Da), a tumor suppressor which regulates cell polarity and energy metabolism." (PMID 37509254, 2023). "In conclusion, we have discovered a new, acquired vulnerability in NSCLC associated with LKB1/STK11 mutations in a subset of NSCLCs that is represented by GR agonist induced CDKN1C expression leading to a host of anti-tumor responses." (PMID 37035141, 2023). "Curiously, both KEAP1 and STK11 mutations are associated with worse prognosis in tumours harbouring KRAS G12C mutations compared to G12V or G12D." (PMID 36864508, 2023). "Circulating tumor DNA analysis of a cohort of 246 NSCLC patients revealed that 90% of patients with an STK11/LKB1 variant demonstrated weight loss at cancer diagnosis." (PMID 37092555, 2023). "Role of tumor STK11/LKB1 loss of function in promoting CC development in an immunocompetent CRC murine model." (PMID 37092555, 2023).